CRNKL1 (crooked neck pre-mRNA splicing factor 1)
Description:
Involved in pre-mRNA splicing process. As a component of the minor spliceosome, involved in the splicing of U12-type introns in pre-mRNAs (Probable).
Synonyms: hCrn; CRN; MSTP021; CLF; SYF3; Clf1; MGCH
Tractability: Small molecule: a structure with a bound ligand is known. PROTAC: ubiquitination databases record sites on it; its protein half-life has been measured.
Gene: Protein-coding gene on chromosome 20 (20,034,368 to 20,056,046, reverse strand). Ensembl gene ENSG00000101343.
Subcellular location: Nucleus; Nucleus speckle
Pathways (Reactome):
Disease: Dengue Virus-Host Interactions
Metabolism of RNA: mRNA Splicing - Major Pathway
Gene Ontology:
Molecular function: protein binding; RNA binding
Biological process: mRNA splicing, via spliceosome; spliceosomal complex assembly; RNA processing
Cellular component: catalytic step 2 spliceosome; nuclear speck; nucleus; post-mRNA release spliceosomal complex; post-spliceosomal complex; spliceosomal complex; U12-type catalytic step 2 spliceosome; U2-type catalytic step 1 spliceosome; U2-type catalytic step 2 spliceosome; nucleoplasm; Prp19 complex
Genetic constraint (gnomAD): Loss-of-function variants: 28 observed, 86.3 expected, observed/expected ratio (o/e) 0.32, 90% interval 0.24 to 0.44. The upper end of that interval is the gene's LOEUF score, 0.44, which puts it in group 1 of 6, group 1 being the genes least tolerant of losing a copy. Missense variants: 579 observed, 771.45 expected, observed/expected ratio (o/e) 0.75, 90% interval 0.7 to 0.8. Synonymous variants: 235 observed, 265.25 expected, observed/expected ratio (o/e) 0.89, 90% interval 0.8 to 0.99.
Homologues: Orthologues: chimpanzee CRNKL1 (99% identical), macaque CRNKL1 (99% identical), dog CRNKL1 (97% identical), pig CRNKL1 (97% identical), mouse Crnkl1 (96% identical), rabbit CRNKL1 (96% identical), rat Crnkl1 (96% identical), guinea pig CRNKL1 (95% identical), rat LOC102548514 (95% identical), tropical clawed frog crnkl1 (90% identical), zebrafish crnkl1 (85% identical), Drosophila melanogaster crn (68% identical), and 1 more. Paralogues in human: XAB2 (25% identical), PRPF6 (21% identical).
Diseases named in the same sentence as CRNKL1 in open-access papers:
CRNKL1 is named in the same sentence as 14 diseases in open-access papers, as found by Europe PMC text mining. Sharing a sentence is not in itself a finding about the gene and the disease. The quoted sentences say what the papers report.
breast carcinoma (2 papers, 2023 to 2025). "This pattern of dependence was similar to that observed for many light genes, including CRNKL1 in breast cancer cell lines and MED14 in leukaemia cell lines." (PMID 38117798, 2023). "In this study, by integrating CRISPR-CAS9 functional genomics (DEPMAP database) and TCGA multi-omics data, seven key genes (CDK7, CLTC, COPB2, CRNKL1, GSPT1, NSF and PSMD12) that are closely related to the proliferation and prognosis of breast cancer were systematically identified." (PMID 40657358, 2025).
bladder carcinoma (1 paper, 2025).
esophageal cancer (1 paper, 2025). A primary or metastatic malignant neoplasm involving the esophagus. "Colony formation assays and cell proliferation growth curves indicated that CRNKL1 can promote esophageal cancer proliferation." (PMID 40282339, 2025). "By integrating bioinformatics, experimental validation, and clinical correlation analyses, we identified six SFs (CRNKL1, SNRPB2, RBMX2, DDX46, PPWD1, and CFAP20) that are aberrantly overexpressed in esophageal cancer and tightly linked to poor prognosis." (PMID 40282339, 2025). "Our findings position CRNKL1 as a prognostic marker and a potential target for immunotherapy in esophageal cancer." (PMID 40282339, 2025). "Our results reveal for the first time that CRNKL1 depletion impaired migration, stemness, and cytoskeletal organization in esophageal cancer cells." (PMID 40282339, 2025). "We selected two of these SFs (SNRPB2, CRNKL1) and validated their aberrant expression in paired esophageal cancer tissues." (PMID 40282339, 2025). "We performed in vitro functional experiments to confirm whether CRNKL1 could affect the phenotype of esophageal cancer cells." (PMID 40282339, 2025). "We find that CRNKL1 was correlated with esophageal cancer tumor grade." (PMID 40282339, 2025). "CRNKL1 and SNRPB2 showed positive correlations with esophageal cancer stemness, suggesting that survival-related SFs may enhance esophageal cancer stemness." (PMID 40282339, 2025). "Exon 11 skipping of CTTN occurred after knockdown of most survival-related SFs (CRNKL1, SNRPB2, PPWD1, RBMX2, and DDX46), while exon 11 inclusion was observed in esophageal cancer in comparison to normal tissue, both in the TCGA database and in our own full-length sequencing data." (PMID 40282339, 2025).
microcephaly (1 paper, 2025). A congenital or acquired developmental disorder in which the circumference of the head is smaller than normal for the person's age and sex. "Together, our genetic and developmental evidence highly support specific variants in CRNKL1 causing a neurogenetic disorder of microcephaly and pontocerebellar hypoplasia." (PMID 40857589, 2025). "Together, our genetic and developmental functional results confirm that variants in CRNKL1 are associated with severe microcephaly, pontocerebellar hypoplasia, and seizures." (PMID 40857589, 2025).
osteoporosis (1 paper, 2022). A condition of reduced bone mass, with decreased cortical thickness and a decrease in the number and size of the trabeculae of cancellous bone (but normal chemical composition), resulting in increased fracture incidence. "CRNKL1 encodes crooked neck pre-mRNA splicing factor 1, which has been reported to be a hub gene in the protein–protein interaction network identified in osteoporosis." (PMID 35309146, 2022).
ovarian carcinoma (1 paper, 2021). A malignant neoplasm originating from the surface ovarian epithelium. "Furthermore, HNRNPC, CRNKL1, PNN and PPIE were also reported to have a high expression and biological function in several cancers including ovarian cancer 21-24." (PMID 33437214, 2021).
virus infection (1 paper, 2021). "This enhancement was not due to an increased susceptibility to virus infection after CRNKL1 siRNA treatment, since green fluorescent protein (GFP) expression levels after transduction with a lentiviral vector encoding the reporter gene from an internal promoter remained unchanged." (PMID 33468685, 2021).
cancer (2 papers, 2021 to 2025). A tumor composed of atypical neoplastic, often pleomorphic cells that invade other tissues. "KEGG analysis revealed that the splicing targets modulated by CRNKL1 are primarily involved in tight junctions, adherens junctions, and proteoglycans in cancer, suggesting that CRNKL1 may be linked to migration, invasion, and metastasis." (PMID 40282339, 2025). "We found that CCL15, a chemokine known to promote an immunosuppressive microenvironment and cancer metastasis, was significantly correlated with CRNKL1, SNRPB2, and PPWD1." (PMID 40282339, 2025). "Sphere formation experiments showed that knockdown of CRNKL1 significantly impaired cancer stemness in KYSE30 and KYSE410 cells." (PMID 40282339, 2025).
infection (2 papers, 2021 to 2025). The state of being infected such as from the introduction of a foreign agent such as serum, vaccine, antigenic substance or organism. "It will also be important to determine whether the observed I73R-mediated host shutoff results from the nuclear retention of spliced host mRNAs during early infection due to CRNKL1 depletion." (PMID 41465200, 2025).
tumor (2 papers, 2019 to 2025). "We explored the relationship between survival-related SFs and ploidy, and found that CRNKL1, SNRPB2, RBMX2, and CFAP20 showed significant positive correlations with tumor ploidy." (PMID 40282339, 2025). "Additionally, several survival-related SFs (CRNKL1 and DDX46) were positively correlated with tumor purity, suggesting lower tumor immune infiltration." (PMID 40282339, 2025).
CRNKL1 also shares sentences with these, for which no sentence is quoted: diabetes (1 paper); head and neck squamous cell carcinoma (1); leukaemia (1); skin cutaneous melanoma (1).